KEAP1 (kelch like ECH associated protein 1)
Diseases named in the same sentence as KEAP1 in open-access papers (continued):
Sharing a sentence is not in itself a finding about the gene and the disease.
diabetic nephropathy (28 papers, 2012 to 2026). "Pharmacological treatment based on inhibition of the NRF2– kelch-like ECH associated protein 1 (KEAP1) signaling pathway has successfully been applied in treatment of diabetic kidney disease." (PMID 36322291, 2022). "Diabetic nephropathy is a well-known microvascular complication of chronic hyperglycemia, and both oxidative stress and an impaired response by the Nrf2/Keap1/ARE system have been implicated in its progression via renal cell apoptosis, fibrosis, and deficiencies in cellular regeneration." (PMID 28913364, 2017). "Regarding the effect of Sestrin2 on autophagic degradation of Keap1, enhancing Sestrin2 expression can simultaneously strengthen Nrf-2-mediated renal protection in diabetic nephropathy." (PMID 36818747, 2023). "Sestrin2 upregulation was shown to accelerate autophagic Keap1 degradation and improve Nrf2-mediated antioxidant response in a rat model of diabetic nephropathy and murine podocyte cell line exposed to high glucose concentration." (PMID 36818747, 2023). "Conversely, inhibition of miR-200a-induced downregulation of Keap1 by LNA-200a abolished the protective effects of Nrf2 on diabetic nephropathy." (PMID 36818747, 2023). "Downregulation of Keap1 by miR-200a also effectively enhanced Nrf2 function and protected against albuminuria, oxidative stress, and fibrosis in streptozotocin-induced diabetic nephropathy." (PMID 36818747, 2023). "We previously showed that miR-200a/141 acted to target Keap1 directly and then regulated Nrf2 under high-glucose conditions, resulting in diabetic nephropathy in mice." (PMID 32802189, 2020). "Actually, in our previous study, we also reported that miR-200a and miR-141 acted to target Keap1 in renal mesangial cells, resulting in profound dysregulations in Keap1-Nrf2 signaling during the development of diabetic nephropathy." (PMID 32802189, 2020). "We now review the biological bases of oxidative stress and its role in kidney diseases, with focus on diabetic nephropathy, as well as the role of the Keap1-Nrf2 pathway and recent clinical trials targeting this pathway with bardoxolone methyl." (PMID 22701794, 2012). "Moreover, miR-200a resulted in Nrf2 activation by targeting Keap1 mRNA and promoting degradation of Keap1 mRNA in diabetic nephropathy." (PMID 31781322, 2019). "Previous reports demonstrate that Keap1 is induced under diabetic nephropathy and then whether BDE-47 as a diabetic prevalence factor regulates the level of Keap1." (PMID 29163754, 2017). "Keap1-Nrf2-ARE pathway is associated with OS, which in the organism can lead to cell damage, leading to a variety of chronic diseases in the body, including renal ischemia/reperfusion injury, diabetic nephropathy, pancreatitis, hepatitis, lung ischemia-reperfusion injury, etc.." (PMID 36408214, 2022).
melanoma (28 papers, 2015 to 2025). A malignant, usually aggressive tumor composed of atypical, neoplastic melanocytes. "In melanoma, a frameshift KEAP1 mutation, leading to the aberrant activation of NRF2, was found to be associated with an increase in chemoresistance to CDDP or DTIC." (PMID 37372043, 2023). "In a subset of melanomas, this is explained by KEAP1 deactivating mutations that have been observed and cause elevated NRF2 expression following transformation to a primary tumor." (PMID 35326683, 2022). "For example, 9/11 BRAF V600E mutations were in melanoma samples, 9/10 KEAP1 mutations were in lung samples and 5/5 VHL mutations were in clear cell renal cancer samples." (PMID 34830758, 2021). "CB-839 treatment significantly suppressed cell growth in a panel of tumor cells including melanoma, bone, colon, renal, squamous, and urinary tract cancers with KEAP1 mutations." (PMID 28967864, 2017). "Our previous study identified a KEAP1 frameshift mutation in ~10% of melanoma cell lines and clinical melanoma specimens." (PMID 27045471, 2016). "Thus, loss of KEAP1 expression contributes toward resistance to ICB in melanoma, both in mouse models and patient datasets, and the impact of both KEAP1 loss and NRF2 activation should be further interrogated as larger clinical datasets are generated." (PMID 36864091, 2023). "Furthermore, the loss of KEAP1 in melanoma was identified as a factor leading to resistance against anti-PD-1 therapy." (PMID 38139110, 2023). "However, when 3-MPA was used to inhibit PCK1, KEAP1 was activated leading to ROS accumulated, which caused oxidative attack to resistant melanoma cells." (PMID 36700470, 2022). "The present study was conducted to clarify whether an HSP90 inhibitor, 17-AAG, efficiently eliminates melanoma with KEAP1 mutation, as the NRF2 target gene, NQO1, is a key enzyme in 17-AAG bioactivation." (PMID 27045471, 2016). "As observed in the present study, KEAP1 mutation-independent NRF2 activation may be evident in a high proportion of NQO1-high melanomas." (PMID 27045471, 2016). "Other signalling pathways, such as NRF2/Keap1, regulate the antioxidant response in melanoma and have an ambivalent function, protecting the healthy melanocyte from stress but also promoting tumour cell survival against ROS-induced damage." (PMID 39594467, 2024). "Intra- and inter-tumor variation in KEAP1 expression thus appears to be a consistent feature in melanoma." (PMID 36864091, 2023). "Epigenetic changes in other KEAP1 regulatory sequences or cofactors, or changes in KEAP1 mRNA stability, are thus likely to drive heterogeneity of KEAP1 expression in melanoma." (PMID 36864091, 2023). "We next asked if KEAP1 expression is associated with immunological phenotypes in melanoma samples, using GSEA for genes ranked by their correlation with KEAP1 expression." (PMID 36864091, 2023). "To further analyze transcriptional downregulation of KEAP1 in melanoma CTCs, we used scRNAseq of ex vivo cultured CTCs, derived from an oligoclonal population of CTCs from a single patient with metastatic melanoma (MEL167)." (PMID 36864091, 2023). "To model the functional impact of KEAP1 expression on melanoma tumor growth and response to immune checkpoint inhibition in vivo, we used the well-established B16-OVA model, in which anti-PD1 antibody treatment mediates a potent anti-tumor response." (PMID 36864091, 2023). "For example, although nobiletin alleviates AKI in UUO mice by suppressing ferroptosis, it induces ferroptosis in melanoma cells through the GSK3β-regulated Keap1/NRF2/HO-1 pathway." (PMID 37739961, 2023). "Using single cell RNA sequencing of melanoma patient-derived circulating tumor cells (CTCs) and functional characterization using mouse melanoma models, we show that the KEAP1/NRF2 pathway modulates sensitivity to ICB, independently of tumorigenesis." (PMID 36864091, 2023).
melanoma (continued). "Moreover, the level of Kelch-like Ech-associated protein-1 (Keap1) was increased, while the level of nuclear factor erythroid 2-related factor 2 (Nrf2), and haem oxygenase-1 (HO-1) was decreased in nobiletin-treated melanoma cells, suggesting that the antioxidant defence system was downregulated." (PMID 35350242, 2022). "Collectively, our results demonstrated that the mechanism of nobiletin-induced ferroptosis involved regulation of the GSK3β-mediated Keap1/Nrf2/HO-1 signalling pathway in human melanoma cells." (PMID 35350242, 2022). "Our results showed that by modulating either NRF2 or KEAP1 in melanoma cells, the whole NRF2 system can be either blocked or enhanced." (PMID 34951143, 2022). "Some genes were mostly restricted to certain subtypes; for example, BRAF mutations occurred mostly in melanoma, VHL mutations in kidney clear cell samples, and KEAP1 mutations were found in lung samples." (PMID 34830758, 2021). "The cBioPortal database (Skin Cutaneous Melanoma, TCGA, PanCancer Atlas, 448 samples) was used to analyze the correlation between xCT expression and selected genes (KEAP1, NRF2, and YKL39) in melanoma patients." (PMID 33959512, 2021). "Enhanced activity of NRF-2 in melanoma was connected to genetic alterations in KEAP1, and was responsible for intrinsic resistance of melanoma cells to cisplatin and dacarbazine." (PMID 32340261, 2020). "Here, KEAP1 and NRF2 mutations are uncommon, although melanomas upregulate several antioxidant pathways including peroxiredoxins, the cysteine/glutathione pathway or NADPH regeneration." (PMID 32978520, 2020). "To determine the level of basal NRF2 protein expression in melanoma, we performed western blots using seven melanoma cell lines, a primary neonatal human epidermal melanocyte (NHEM) cell line and the KEAP1-mutated A549 NSCLC cell line as positive control." (PMID 32978520, 2020). "NQO1 is highly expressed in normal melanocytes and in several melanoma cell lines despite the presence of wild-type KEAP1, and the NQO1 expression is dependent on NRF2 activation." (PMID 27045471, 2016). "In both melanoma and NSCLC, IC50 values for cell lines with KEAP1 mutation and high NQO1 expression were lower than those of cell lines with low NQO1 expression." (PMID 27045471, 2016). "Overexpression of NQO1 in KEAP1 wild-type melanoma cell lines and normal melanocyte was dependent on NRF2." (PMID 27045471, 2016). "Previously, we reported the presence of frame shift mutations in the KEAP1 gene and accumulation of NRF2 in melanoma tissues and melanoma cell lines." (PMID 27045471, 2016). "Pretreatment with the NQO1 inhibitor increased the IC50 of 17-AAG by more than 2-fold in all melanoma cell lines tested and in NSCLC cell lines with KEAP1 mutation." (PMID 27045471, 2016). "Previously, we reported that KEAP1 mutation elicits constitutive NRF2 activation and resistance to cisplatin (CDDP) and dacarbazine (DTIC) in human melanomas." (PMID 27045471, 2016). "Melanoma cell line A7 and NSCLC cell lines A549 and H460 harbor KEAP1 loss-of-function mutation and express abundant NRF2 and NQO1 in comparison with other cell lines." (PMID 27045471, 2016). "Here we show that melanoma cells exhibit an oxidative stress phenotype compared with normal melanocytes, as evidenced by increased total cellular ROS, KEAP1/NRF2 pathway activity, protein damage, and elevated oxidized glutathione." (PMID 25749517, 2015). "Moreover, Nob has been found to induce ferroptosis in human melanoma cells by controlling the GSK3 beta-mediated Keap1/Nrf2/HO-1 signaling pathways, which are critical in inhibiting tumor growth." (PMID 38474379, 2024). "Indeed, the stabilization of NRF2 resulting from KEAP1 knockout is sufficient to completely ablate the sensitivity of mouse melanomas to anti-PD1 treatment." (PMID 36864091, 2023). "In addition to heterogeneous expression within melanoma CTCs, we find large variation in total KEAP1 expression across microarrays of human primary melanomas." (PMID 36864091, 2023).
melanoma (continued). "Thus, loss of KEAP1 expression and associated upregulation of NRF2 signaling within individual melanoma CTCs are associated with poor response to ICB in our CTC cohort." (PMID 36864091, 2023). "Notably, the “Hallmark Interferon Gamma Response” and “Hallmark TNFA Signaling via NFKB” gene signatures correlated with KEAP1 expression in melanoma CTCs and in tumor samples and cell lines from the Cancer Genome Atlas (TCGA)." (PMID 36864091, 2023). "The link between KEAP1 loss and altered cytokine expression is supported by interactions between NRF2 and NF-κB14, and our findings in melanoma are consistent with a preliminary report showing that KEAP1 mutations cause resistance to anti-PD1 treatment in a transgenic mouse model of lung cancer." (PMID 36864091, 2023). "Taken together, our results demonstrated that nobiletin could induce ferroptosis by regulating the GSK3β-mediated Keap1/Nrf2/HO-1 signalling pathway in human melanoma cells." (PMID 35350242, 2022). "Our research revealed that GSK3β could mediate the regulation of the Keap1/Nrf2/HO-1 signalling pathway in nobiletin-treated melanoma cells." (PMID 35350242, 2022). "Given the previous work that described how oxidative stress and the NRF2 regulator KEAP1 regulated IFNγ-mediated MHCII expression in human melanoma cells, NRF2 regulation and redox dysregulation could explain a possible mechanism for MED16 control of MHCII." (PMID 34747695, 2021). "A better understanding of how the NRF2/Keap1 axis functions at the molecular level and how it connects to the glutamatergic pathway in melanoma may help uncover novel regulatory mechanisms of GLS-mediated tumorigenesis." (PMID 32937954, 2020). "To assess whether NRF2 promotes glutamine dependency in other KEAP1 mutant cancers, we tested CB-839 on a panel of human cancer cell lines with WT or mutant KEAP1, including melanoma, bone, colon, renal, squamous and urinary tract cancers." (PMID 28967864, 2017). "We attempted to clarify whether endogenous ROS or the PI3K/AKT pathway might activate NRF2 in KEAP1 wild-type melanoma cells." (PMID 27045471, 2016). "The present study was conducted to investigate whether melanoma and NSCLC cell lines harboring KEAP1 mutation would be sensitive to 17-AAG." (PMID 27045471, 2016). "We then determined whether NQO1 overexpression is dependent on NRF2 transcriptional activity in melanocytes and melanoma harboring wild-type KEAP1." (PMID 27045471, 2016). "The role of the NRF2/KEAP1 pathway in melanoma development is twofold: on the one hand, its potential antioxidant function reduces the likelihood of cancer; however, there is evidence that this pathway is also used as a mechanism of resistance to ROS damage in melanoma." (PMID 39594467, 2024). "However, we can certainly exclude the intervention of post-translational mechanisms leading to a decrease in KEAP1 content, such as the p62 Nrf2-KEAP2 disruptor, or the dysregulation of microRNA targeting KEAP1, since the KEAP1 protein content remains unchanged in all melanoma clones studied here." (PMID 37372043, 2023). "Somatic Nrf2 gain-of-function and Keap1 loss-of-function mutations are frequent in tumors and correlate with chemo/radioresistance and poor clinical outcome; however, even if Keap1 missense or nonsense mutations have also been reported, in melanoma, Keap1 and Nrf2 mutations are not frequent." (PMID 34943045, 2021). "Expression of NRF2 and NQO1 was variable among melanoma cell lines without KEAP1 or NRF2 mutation." (PMID 27045471, 2016). "The highest correlations observed with HMOX-1 in patients with melanoma were with FZD2 (rho = 0.54), KEAP1 (rho = 0.59), MAPK13 (rho = 0.68), the “ferroptosis” gene FTL (rho = 0.58), and CHUK (rho = −0.50)." (PMID 35053476, 2022). "In most human melanomas the NRF2 system is not constitutively activated, as mutations in NRF2 and KEAP1 are only sporadic." (PMID 34951143, 2022).
melanoma (continued). "NQO1 was found to be highly expressed in normal melanocytes and several melanoma cell lines, irrespective of the presence of wild-type KEAP1, and they were also 17-AAG-sensitive in comparison with NQO1-low cell lines." (PMID 27045471, 2016). "Expression of NRF2 and NQO1 proteins in normal melanocytes, melanoma and NSCLC cell lines with or without KEAP1 mutations was compared by immunoblotting." (PMID 27045471, 2016). "However, while we find methylation of the KEAP1 promoter to be highly variable across single melanoma CTCs, neither promoter methylation nor intragenic methylation is correlated with expression of KEAP1 mRNA at the single cell level." (PMID 36864091, 2023). "Taken together, the observation that mutations in the Kelch_1 domain of KLHL4 align precisely with hotspot mutations in KEAP1, in tandem with a lack of reports of oncogenic mutations in KLHL4 in melanoma, make these mutations an appealing subject for future investigation." (PMID 26590264, 2016). "However in B16-OVA melanoma cells, NRF2 knockout alone does not significantly inhibit primary tumor growth in the absence of anti-PD1, nor does KEAP1 knockout enhance tumor growth in the absence of treatment." (PMID 36864091, 2023). "In particular, in BRAF V600E mutant melanoma, the MAPK activated pathway leads to hyperphosphorylation of FAM129B, which in turn can compete with Nrf2 for the binding to Keap1; in the absence of its inhibitor Keap1, Nrf2 protein is more stable; thus, its level can increase." (PMID 34943045, 2021).
lung squamous cell carcinoma (27 papers, 2012 to 2025). "It has been known that KEAP1 somatic mutations occur more frequently in LUAD39 than lung squamous cell carcinoma." (PMID 41035689, 2025). "One lung squamous cell carcinoma study showed that KEAP1 mutation was associated with dramatically lower CD8+ TIL density (P = 0.005)." (PMID 38884095, 2024). "KEAP1/NFE2L2 had higher mutation frequency in lung squamous cell carcinoma (OAK/POPLAR, P = 0.05; OAK, P = 0.044; POPLAR, P = 0.069)." (PMID 34381706, 2021). "High-frequency somatic mutations in KEAP1/NRF2 (27.9%) have been identified in lung squamous cell carcinoma." (PMID 32576270, 2020). "Kelch-like ECH-associated protein 1 (Keap1)/nuclear factor erythroid 2-like factor 2 (Nrf2)/Cullin3 pathway alterations occur in a third of squamous cell lung cancer according to TCGA discoveries." (PMID 26922479, 2016). "Additionally, in ten patients with lung squamous cell carcinoma, we identified mutations in KEAP1/NFE2L2 that influenced the expression of target genes in vivo and in vitro." (PMID 32629428, 2020). "In Lung Squamous Cell Carcinoma (LSCC) mice models developed by KEAP1 deletion, the persistent activation of NRF2 has been suggested to contribute to increased tumor formation, metastasis, and resistance to oxidative stress and irradiation." (PMID 32751080, 2020). "A very recent comprehensive genomic characterisation study on squamous cell lung cancer conducted by the Cancer Genome Atlas Research Network reported the occurrence of mutations in NRF2, KEAP1, or CUL3 in 34% of 178 lung squamous cell carcinomas." (PMID 24278719, 2012). "For example, there is a strong interaction between mutations and CNA loss in KEAP1 in lung squamous cell carcinoma (LUSC) but not in samples that also carry a PTEN mutation." (PMID 34862370, 2021). "Moreover, these two NRF2 target genes are also highly upregulated in data from TCGA patients with mutated KEAP1 and NRF2 in lung squamous cell carcinoma, LUAD, and head and neck squamous cell carcinoma." (PMID 29050246, 2017). "The frequency of disruption for ovarian tumors was comparable to the high frequencies observed in uterine carcinoma and lung squamous cell carcinoma (LUSC), where disruption of the KEAP1/CUL3/RBX1 E3-ubiquitin ligase complex is well established." (PMID 25114896, 2014).